TBC1D4 (TBC1 domain family member 4)
Diseases named in the same sentence as TBC1D4 in open-access papers (continued):
Sharing a sentence is not in itself a finding about the gene and the disease.
metabolic syndrome (2 papers, 2022 to 2023). A cluster of metabolic risk factors for CARDIOVASCULAR DISEASES and TYPE 2 DIABETES MELLITUS. "Interestingly, in the current study we observed an increased expression of AS160/TBC1D4 in the adipocytes derived from ADMSCs of obese patients (especially from individuals with metabolic syndrome)." (PMID 35563741, 2022). "An examination of TBC1D4 levels revealed its greater expression in the adipocytes derived from the obese patients (with and without metabolic syndrome) when compared to their lean analogues." (PMID 35563741, 2022).
myocardial infarction (2 papers, 2023 to 2024). Gross necrosis of the myocardium, as a result of interruption of the blood supply to the area, as in coronary thrombosis. "Indeed, a recent study showed that Tbc1d4 deficiency worsened cardiac damage following myocardial infarction." (PMID 39026321, 2024). "Next, the impact of Tbc1d4 knockout on cardiac function in vivo and the response to myocardial infarction were assessed." (PMID 36707786, 2023). "In the present study, we demonstrate that lack of the insulin signaling protein TBC1D4 in mice abrogates cardiac glucose uptake in response to insulin and aggravates cardiac damage after myocardial infarction." (PMID 36707786, 2023).
acanthosis nigricans (1 paper, 2013). A melanotic cutaneous lesion that develops in the axilla and other body folds. "In line with these in vitro findings, a loss-of-function nonsense mutation in the TBC1D4 gene in a severely insulin-resistant Acanthosis nigricans patient was reported." (PMID 24280290, 2013).
atherosclerosis (1 paper, 2022). A disease characterized by the build-up of fatty material and calcium deposition in the arterial wall resulting in partial or complete occlusion of the arterial lumen. "Cluster 5 showed a gene expression profile that was characterized by the expression of Btla, Ccr7, Tbc1d4, Ccl22, and Ly6d revealing a population of MoDC/DC cells present in the aortas that were independent of the atherosclerosis predisposition or the diet." (PMID 35159221, 2022).
cardiac hypertrophy (1 paper, 2023). "Ablation of Tbc1d4 also impacts transcription of genes in canonical pathways annotated for CVD-associated phenotypes (cardiac hypertrophy signaling) prior to I/R intervention." (PMID 36707786, 2023).
COVID-19 (1 paper, 2024). A disease caused by infection with severe acute respiratory syndrome coronavirus 2. "Among the potential genes around the top-10 scored SNPs, we identified that the TBC1D4 gene, which regulates glucose homeostasis, is potentially associated with COVID-19 comorbidities." (PMID 39696471, 2024).
dermatomyositis (1 paper, 2024). Dermatomyositis (DM) is a type of idiopathic inflammatory myopathy characterized by evocative skin lesions and symmetrical proximal muscle weakness. "Under such a model is where our results may be the most relevant, as GLUT4 and its associated trafficking genes (e.g., TBC1D4/AS160) are significantly downregulated in the muscle of dermatomyositis patients presenting with exaggerated interferon signatures." (PMID 38883790, 2024).
dilated cardiomyopathy (1 paper, 2015). Cardiomyopathy which is characterized by dilation and contractile dysfunction of the left and right ventricles. "It is possible that factors other than Thr649 phosphorylation of AS160/TBC1D4 mediate the pathogenesis of dilated cardiomyopathy and cardiac infarction due to the loss of PKB/Akt." (PMID 25923736, 2015).
generalized lipodystrophy (1 paper, 2021). Almost complete absence of subcutaneous and/or visceral adipose tissue. "They included 65 patients with generalized lipodystrophy, 87 with partial lipodystrophy and 42 with defective insulin signaling, of whom 16 had a genetic INSR pathogenic variant, 25 had type B IR and 1 had a TBC1D4 defect." (PMID 33901270, 2021).
hyperandrogenism (1 paper, 2021). Excessive secretion of androgens from the adrenal glands or gonads. "We now describe 6 patients (including P13) with SIR (2 with type B IR, 2 with pathogenic INSR variants, 1 with a pathogenic variant in TBC1D4, and 1 with acquired partial lipodystrophy associated with juvenile dermatomyositis) who received GnRH analogue therapy for management of hyperandrogenism." (PMID 33901270, 2021).
ischemic heart disease (1 paper, 2020). "Compared to non-carriers, HO carriers had more frequent ischemic heart disease (HO 46.7% vs WT 32.7%), CVD deaths (33.3% vs 27.2) and fewer stroke diagnoses (HO 20.0% vs WT 35.5%), corresponding well to the fact that TBC1D4 is expressed in heart and muscle tissue and not in the brain." (PMID 33328529, 2020).
overgrowth syndrome (1 paper, 2022). A group of syndromes caused by genetic birth defects that may lead to the development of malignancies. "In conclusion, customized panel-gene deep-sequencing enhanced the genetic diagnosis in patients with lateralized overgrowth syndrome, which furthermore identified the potentially causative new variants in MAP2K3 and TBC1D4." (PMID 36175890, 2022).
SHORT syndrome (1 paper, 2022). A rare disorder characterized by multiple congenital anomalies, including short stature, hyperextensibility of joints, ocular depression, Rieger anomaly and teething delay in which the cause of the disease is a mutation in PIK3R1 gene. "Hereditary insulin resistance syndromes include genetic syndromes caused by INSR mutations, SHORT syndromes caused by PIK3R1 abnormalities, and conditions caused by AKT2, TBC1D4, or PRKCE abnormalities." (PMID 36626508, 2022).
vascular malformation (1 paper, 2022). A non-neoplastic disorder that is the result of defects of vascular morphogenesis. "The identified PIK3CA mutations have been previously reported in other patients with PROS, and the KRAS and TEK mutations in patients with vascular malformation, but the MAP2K3 and TBC1D4 mutations have not been previously reported." (PMID 36175890, 2022).
tumor (7 papers, 2011 to 2025). "By real-time qPCR, we further examined the expression of selected genes (Pkm, Ppp1r13l, Vamp3, Ctnnb1, Tbc1d4, Ppp1r21, C1qtnf9, Fgf3 and Efemp2) that are known to be involved in the tumor development or potentially relevant for establishment of malignant transformation." (PMID 29073177, 2017). "TBC1D4 Thr642 has also been reported to be a substrate for p90 ribosomal S6 kinase 1 and serum- and glucocorticoid-induced protein kinase 1, the activity of which may be elevated in these tumours." (PMID 21505451, 2011). "We observed a higher mRNA expression of TBC1D10C, TBC1D4, TBC1D12, TBCK, TBC1D5, TBC1D30 and a lower expression of TBC1D24 in patients with tumor compared with tumor free patients." (PMID 33194704, 2020). "We undertook a detailed examination of the phosphorylation of three well-characterised Akt substrates in the tumour samples: PRAS40 (on Thr246), TSC2 (on Ser939) and TBC1D4 (on Thr642)." (PMID 21505451, 2011). "These genes, such as RFC1, XPO4, THEGL, SLC19A3, TBC1D4, and KCNH5, may have specific functions in metastatic tumour cells." (PMID 34507604, 2021).
cancer (5 papers, 2012 to 2025). A tumor composed of atypical neoplastic, often pleomorphic cells that invade other tissues. "Collectively, the splicing modulation of VPS39, ZNF207, and TBC1D4 in curcumin-treated HNC cells provides the basis for future investigation of the role of cancer-specific isoforms of these genes in tumorigenesis." (PMID 31675998, 2019).
infection (3 papers, 2019 to 2025). The state of being infected such as from the introduction of a foreign agent such as serum, vaccine, antigenic substance or organism. "It has been proposed that TBC-11/AS160/TBC1D4 acts as a GAP (GTPase activating protein) for RAB-10; however, the mRNA level of TBC-11 was not noticeably affected by infection." (PMID 39087719, 2025).
TBC1D4 also shares sentences with these, for which no sentence is quoted: neuroblastoma (2 papers); acquired lipodystrophy (1); bladder cancer (1); breast carcinoma (1); cardiac ischemia (1); chlamydial infection (1); cholangiocarcinoma (1); glioblastoma multiforme (1); Hyperinsulinemia (1); hyperlipidemia (1); juvenile dermatomyositis (1); keratoconus (1); melanoma (1); metabolic disorders (1); MODY (1); movement disorder (1); multiple lipomatosis (1); multiple myeloma (1); myeloma (1); Parkinson’s (1); partial lipodystrophy (1); prediabetes (1); Sepsis (1); skin cutaneous melanoma (1); Stroke (1).